GFAP (glial fibrillary acidic protein)
Diseases named in the same sentence as GFAP in open-access papers (continued):
Sharing a sentence is not in itself a finding about the gene and the disease.
Ataxia (36 papers, 2013 to 2026). Ataxia refers to impaired coordination of voluntary muscle movement. "Gys1 deficiency in either PCs or GFAP-positive cells reduced anxiety-like behavior, whereas combined deletion caused PC degeneration and ataxia." (PMID 41890976, 2026). "Our search analysis revealed that bulbar signs 115/212 (54.24%), ataxia 74/212 (34.9%) and spasticity 59/212 (27.83%) were the dominant clinical symptoms among carrier of GFAP variants." (PMID 36088400, 2022). "Here, we show that a 68-year-old male with ataxia and atrophy of the medulla oblongata, upper cervical cord and the cerebellar hemispheres on brain MRI harbors a p.Asp128Asn GFAP mutation." (PMID 28882119, 2017). "Conditionally deleting KIR4.1 from GFAP (glial fibrillary acidic protein)-positive astrocytes in mice also caused impaired K+ and glutamate uptake, leading to ataxia, seizures, and premature death." (PMID 27729847, 2016). "Increased expression of the glial fibrillary acidic protein (GFAP), astrogliosis, and thickening of BG processes were also observed in regions with extensive PC loss in a PC-specific Tmem30a KO mouse model that displays early-onset ataxia." (PMID 32168822, 2020). "GFAP variants affecting the p.Arg88 codon have been already highlighted in patients affected by juvenile and adult-onset ALXDRD, showing bulbar signs, ataxia and spasticity as pivotal clinical symptoms." (PMID 40208338, 2025). "While untreated and short-term PLX5622-treated WT and GFAP-IL6 mice had a median clinical score of zero during the course of the experiment, both untreated and short-term PLX5622-treated GFAP-IFN mice showed signs of mild ataxia beginning at six weeks." (PMID 36389783, 2022). "Specifically, the number of microglia that expressed IBA1 was increased, as was the expression of GFAP in the cerebellum of Smox/Sat1-dKO mice as early as 8 weeks of age, and this correlated with the severity of ataxia." (PMID 33054763, 2020). "mGFAP:CKO mutants began to develop ataxia at 6 weeks and displayed astrogliosis which can be identified using GFAP antibodies." (PMID 25962146, 2015). "Conversely, chronic and elevated levels of IFN-α in the CNS of GFAP-IFNhi mice lead to epileptic seizures, ataxia and increased mortality, accompanied by severe neuropathological changes, including progressive encephalopathy, calcification, and microangiopathy." (PMID 40613088, 2025). "Furthermore, deletion of Fxn during development in mouse cells with an active GFAP promoter, predominantly astrocytes, induces severe ataxia and premature death, primarily impacting the survival of cerebellar astrocytes." (PMID 39648860, 2025). "However, at 12 weeks of age, we found elevated levels of GFAP and an increased number of microglia in Sel1LPcp2Cre mice, which correlated with a reduction in the number of Purkinje cells and the development of ataxia." (PMID 39352758, 2024). "Similar observations have previously been made in a small cohort of spinocerebellar ataxia patients, and it has been suggested that GFAP may not only be marker of astrocytic damage, but instead also a marker of astrocyte activation." (PMID 30425621, 2018). "Therefore, further relationships between GFAP-IgG and ataxia need to be discussed." (PMID 40735311, 2025). "Indeed, selective ablation of mouse Fxn in GFAP-expressing precursor cells causes alterations selectively in cerebellar astrocytes, but not in forebrain astrocytes, leading to severe ataxia and early death." (PMID 39648860, 2025). "Notably, in GFAP/IKK2-CA animals we found a pronounced downregulation of EAAT1 and EAAT2 already at 10 weeks correlating with transgene expression and in line with a potential pathogenic role in ataxia and Purkinje cell loss." (PMID 28193238, 2017). "Relative to GFAP-WT mice, GFAP-IL6 mice exhibited a mild ataxia by 24 weeks of age, and occasionally, tonic seizures were observed, in line with previous observations." (PMID 40613088, 2025).
Ataxia (continued). "On the other hand, GFAP-IFN mice exhibit a cerebral interferonopathy characterized by stunted growth, neuronal hyperexcitability, cognitive dysfunction, ataxia, convulsive seizures and increased mortality." (PMID 35429976, 2022). "Unique presenting symptoms of gastrointestinal dysfunction, dysphagia and ataxia were seen in the cases with antibodies against DPPX, IgLON5, and GFAP, respectively." (PMID 33692738, 2021). "A genetic screening for ataxia covering nearly 50 genes (next generation sequencing panel) ruled out pathogenic mutations associated with spinocerebellar ataxia (SCA) as well as familial PAPT forms (POLG, GFAP, and SPG7)." (PMID 39450592, 2025). "A non-significant increase in glial fibrillary acidic protein expression was detected in the parietal cortex of GA patients relative to ataxia controls (P = 0.0505), but not compared with healthy controls (P = 0.4057)." (PMID 38510211, 2024). "As the symptoms worsened rapidly, a novel SACS mutation (c.4003 G>A, p.1335 Val>Ile, Heterozygous) was discovered using WES, although no pathogenic mutations with low frequency were found in ataxia-related genes, such as SPG7, FXN, and GFAP." (PMID 38132465, 2023). "TMEV infected, ganciclovir treated, GFAP-transgenic mice (GSTG) showed a significant deterioration of clinical signs including reduced general condition, shaggy fur, waddling gait, and progressive ataxia starting at 71 dpi." (PMID 35714111, 2022). "Delaney and colleagues used ganciclovir to inhibit cell division of GFAP-positive cells in neonatal GFAP-HSV-TK mice, and demonstrated that astrocyte reduction in newborn pups results in ataxia, neuronal excitotoxicity and a disorganization of Purkinje cells and radial glia." (PMID 23305182, 2013). "For instance, transgenic ablation targeting the astrocyte-specific marker glial fibrillary acidic protein (GFAP) has demonstrated significant neurodevelopmental deficits, particularly in the cerebellum, resulting in perturbation of cellular layers, neuronal degeneration, and severe ataxia." (PMID 38046904, 2022). "Similarly, astrocyte-specific deletion of Kcnj10 using GFAP-cre mice results in premature lethality, epileptic seizures, and severe ataxia, none of which were observed with Kir4.1 deletion using Fabp7-CreER2 mice." (PMID 35997251, 2022). "The lack of associations with GFAP and MBP is consistent with the primary targeting of neurons in OPIDP, although the earlier study did show associations with anti-MBP, secondary myelin involvement, and scored clinical ataxia." (PMID 25045531, 2014). "Postnatal analysis of mice expressing a version of glial fibrillary acidic protein (GFAP) promoter-directed Cre did not detect significant alterations in cell proliferation, but observed other phenotypes including seizures, ataxia, and macrocephaly." (PMID 24860420, 2014). "Titers of anti-NF, but not GFAP or MBP, NAb significantly correlated with changes in gait considered indicative of ataxia in OPIDP, decrease in stride length, and increase in width." (PMID 25045531, 2014).
neuromyelitis optica spectrum disorder (35 papers, 2013 to 2025). "Serum glial fibrillary acidic protein (sGFAP) is associated with disease activity in aquaporin-4-immunoglobulin G-seropositive neuromyelitis optica spectrum disorders (AQP4-IgG+NMOSD)." (PMID 40693183, 2025). "GFAP, though a more recent addition to clinical practice, is gaining recognition for its diagnostic utility in conditions such as neuromyelitis optica (NMO) and other CNS disorders." (PMID 40823306, 2025). "Another example is serum measurement of GFAP, that is associated with both disease activity and severity in neuromyelitis optica, an inflammatory disorder targeting astrocytes, leading to attacks of longitudinal myelitis and optic neuritis." (PMID 35765081, 2022). "Neuromyelitis optica is an antibody-mediated autoimmune inflammatory disease of the CNS, caused by the loss of aquaporin-4 and GFAP that are mainly expressed by astrocytes." (PMID 34804074, 2021). "AQP4 and GFAP antibodies serve as key biomarkers for neuromyelitis optica spectrum disorders (NMOSD) and autoimmune GFAP astrocytopathy, respectively—two classical astrocytopathies." (PMID 40688088, 2025). "Area postrema syndrome (APS) is one of the clinical presentations of neuromyelitis optica spectrum disorders (NMOSD) and has rarely been associated with glial fibrillary acidic protein (GFAP) antibodies." (PMID 38757769, 2024). "Two patients developed APS, as previously reported, implying that APS should not only be considered as a diagnosis of neuromyelitis optica spectrum disorders (NMOSD) but should also be tested for anti-GFAP antibodies." (PMID 37205100, 2023). "It has been indicated that inflammatory diseases of CNS such as neuromyelitis optica and MS showed high levels of GFAP in CSF." (PMID 37886003, 2023). "One example, therefore, is the very high levels of GFAP in the serum of neuromyelitis optica patients, where especially aquaporin-4 positive astrocytes are damaged." (PMID 32765393, 2020). "This study aimed to evaluate the potential utility of glial fibrillary acidic protein (GFAP) and neurofilament light chain (NfL) as biomarkers of disease activity in AQP4-IgG-positive neuromyelitis optica spectrum disorder (NMOSD) and MOG antibody-associated disease (MOGAD)." (PMID 41155859, 2025). "Type-I IFN contributes to the disease progression, as loss of aquaporin-4 and GFAP following intracerebral injection of IgG from a neuromyelitis optica patient was alleviated in mice lacking IFNAR." (PMID 34804074, 2021). "The relationship between plasma GFAP and lower myelin content in the temporal lobe underscores the well documented relationship between astrocyte injury, demyelination, and oligodendrocyte degeneration observed in inflammatory conditions of the CNS, such as neuromyelitis optica." (PMID 36762407, 2023). "Thus, GFAP levels in these body fluids may reflect the disease state of neuromyelitis optica spectrum disorder (NMOSD), which includes astrocytopathy, characterized by pathogenic antibodies against aquaporin 4 located on astrocytes." (PMID 35370870, 2022). "In neuromyelitis optica spectrum disorder (NMOSD), intrathecal IL-6 and GFAP are elevated during attacks." (PMID 40175894, 2025). "The coexistence of spinal cord lesions and GFAP/AQP4 antibody seropositivity in this case necessitated critical differentiation from primary autoimmune astrocytopathies and neuromyelitis optica spectrum disorders (NMOSD)." (PMID 40688088, 2025). "Potential differentials included GFAP astrocytopathy, anti-NMDAR encephalitis, MOG antibody disease, and neuromyelitis optica spectrum disorder (NMOSD)." (PMID 41497949, 2025). "GFAP CSF antibodies have been found in the setting of diverse neoplasms, HSV infection, and other neurologic autoimmune diseases such as neuromyelitis optica and anti-N-methyl D- (NMDA) receptor encephalitis." (PMID 36737749, 2023).
neuromyelitis optica spectrum disorder (continued). "As an intracellular protein, GFAP cannot be up- or down-regulated on the cell surface, and a similar situation also applies to AQP4 in neuromyelitis optica." (PMID 34880859, 2021). "The novel concept of astrocytopathy, including neuromyelitis optica spectrum disorders (NMOSD) and autoimmune glial fibrillary acidic protein (GFAP) astrocytopathy, was recently suggested." (PMID 30568655, 2018).
autism (34 papers, 2010 to 2025). Persistent deficits in social interaction and communication and interaction as well as a markedly restricted repertoire of activity and interest as well as repetitive patterns of behavior. "This work reports the discovery of elevated levels of sAPPα and α-CTF in the insular cortex of autism patients and suggests increased GFAP expression-associated hypoactivity and social deficits in mice designed to over-express hsAPP in brain tissues." (PMID 23840007, 2013). "First, we conducted autism-associated behavioral tests in GFAP-Dscam f/f and control mice." (PMID 34848499, 2022). "Consistent with previous reports of increased GFAP expression in various brain regions of individuals with autism, cortical astrocytes from VPA-exposed ASD mice exhibited marked GFAP upregulation, indicative of astrocyte activation." (PMID 41367497, 2025). "The high level of GFAP in the brain of autistic animals is expected because increased GFAP in the cerebellum has been reported in an individual with autism." (PMID 35334937, 2022). "Our study showed that PPA treatment significantly decreased the expression of MMP-9, BDNF, ICAM, Synapsin I, PSD-93, and PSD-95 but elevated GFAP in the brain of PPA-induced PPA-induced autism-like rats." (PMID 35334937, 2022). "The aim of this investigation was to assess astrocyte density and morphology within the white matter of the DLPFC in autism compared to age- and gender-matched controls using GFAP as a cellular astrocyte marker." (PMID 29234492, 2017). "This was followed by Laurence and Fatemi’s results, also demonstrating increased protein levels of GFAP in the superior frontal, parietal and cerebellar cortex in autism." (PMID 29234492, 2017). "Further support for prefrontal and cerebellar changes were demonstrated by a quantitative real-time polymerase chain reaction (qPCR) investigation showing increased GFAP expression in both regions in autism compared to controls." (PMID 29234492, 2017). "DLPFC formalin-fixed sections containing white matter from individuals with autism (n = 8, age = 4–51 years) and age-matched controls (n = 7, age = 4–46 years) were immunostained for glial fibrillary acidic protein (GFAP)." (PMID 29234492, 2017). "P6 treatment significantly reduced GFAP levels (autism serum vs autism serum+P6 group, Bonferroni’s post-hoc test, p>0.05, Student’s t-test, p = 0.049)." (PMID 25769033, 2015). "We further evaluated the effect of autism sera treatment on two markers of neuroinflammation i.e., glial fibrillary acidic protein, GFAP, a marker of astrocytes, and Iba1, a marker of microglia, in the cerebral cortex of young rats by Western blots." (PMID 25769033, 2015). "Proteomic profiling studies have shown that brain-derived neurotrophic factor (BDNF) and glial fibrillary acidic protein (GFAP) are altered in autism patients." (PMID 25126406, 2014). "Our findings parallel those of previous studies, which have shown increased expression of GFAP protein in the cerebellum and cortex of patients of autism through IHC staining, western blotting, and mRNA expression." (PMID 24410870, 2014). "In post-mortem cerebellum, the expression of astrocyte marker GFAP was also significantly higher in autism samples than in healthy controls (2.63-fold, P = 0.0022)." (PMID 24410870, 2014). "Our results for FMRP, mGluR5 and GFAP confirm our previous work in the cerebellar vermis of people with autism." (PMID 21548960, 2011). "This increased level of GFAP is consistent with previous findings of astroglial activation in the brains of individuals with autism, suggesting dysregulation of the immune system." (PMID 21548960, 2011). "We observed significantly reduced levels of protein for FMRP in adults with autism, significantly increased levels of protein for mGluR5 in children with autism and significantly increased levels of GFAP in adults and children with autism." (PMID 21548960, 2011).
autism (continued). "Our finding regarding GFAP confirms our earlier findings of significant elevation of GFAP in BA9 of a different set of people with autism." (PMID 21548960, 2011). "Other brain auto-antibodies such as anti-neuron-axon filament protein, anti-glial fibrillary acidic protein and anti-caudate nucleus were also reported to be increased in patients with autism." (PMID 21696608, 2011). "A role for neuroglial activation in autism is suggested by altered expression of GFAP, a marker of astroglial in brain and CSF of subjects with autism." (PMID 21119878, 2010). "The higher levels of MAP-2, NFP, MBP, MAG, α-synuclein S100B and GFAP (3.2 to 4.8-fold) autoantibodies reported in ASD children warrant further research for developing autoantibodies screening as a biomarker for detection of early autism." (PMID 31035713, 2019). "In Autism, increase in autoantibodies of GFAP has also been found in plasma." (PMID 30526520, 2018). "Based on previous evidence demonstrating increased GFAP within the brain in autism, we hypothesized that we would observe an increased density of astrocytes in the white matter of the DLPFC of individuals with autism." (PMID 29234492, 2017). "The levels of GFAP were marginally increased in autism serum group compared to sham animals (GFAP, ANOVA, p = 0.0104, Bonferroni’s post-hoc test, p>0.05, Student’s t-test, p = 0.073) and significantly increased compared to control serum group (Bonferroni’s post-hoc test, p<0.05)." (PMID 25769033, 2015). "Increased GFAP level observed in the present study in autism sera treated rats could signify gliosis, reactive injury and impaired neuronal migration processes." (PMID 25769033, 2015). "It is tempting to speculate that RAC1 overexpression in autism may also be responsible for increased glial fibrillary acidic protein (GFAP) immunoreactivity detected in the brains of subjects with autism." (PMID 23803181, 2013). "Increased AAB reactivities against GFAP could be found in the serum of autism and AMD patients." (PMID 34943212, 2021). "In addition, evidence for astrocyte dysfunction/activation has also come from a post-mortem brain investigation in autism demonstrating increased mRNA levels of GFAP and observations of astrogliosis in the cerebellar white matter and subcortical white matter within the frontal lobe." (PMID 31434868, 2019). "In addition to GFAP, altered expression of AQP4 has been associated with this neurologic disease; in particular AQP4 expression was decreased in cerebellum of subjects with autism." (PMID 21119878, 2010). "Many earlier studies reported the increase in GFAP expression in various diseases such as Alzheimer’s, Amyotrophic lateral sclerosis (ALS), Parkinson’s, Pick’s, Huntington’s and Autism." (PMID 30526520, 2018). "GFAP was found to be significantly elevated in BA9 of both children (136%, P < 0.012) and adults (58%, P < 0.033) with autism." (PMID 21548960, 2011). "Notably, the dysfunctional Notch pathway has a potential correlation with autism, and via its pleiotropic actions, the activated Notch/NICD axis has been reported to promote the formation of GFAP by activating NF-κB p65." (PMID 38137376, 2023). "PPA-induced autism-like rats administered with MgB (at all doses) exhibited a significant increase in the expression levels of BDNF, GAP, ICAM, PSD-93, and PSD-95 in the brain and decreased GFAP expression, compared to the control group." (PMID 35334937, 2022). "Our findings are in keeping with recent studies demonstrating no alteration in astrocyte number and astrocyte somal size in the amygdala in autism, as well as no increase in GFAP mRNA and protein in the anterior PFC and ACC." (PMID 29234492, 2017). "There are no data about astrocytosis within the amygdala, but Laurence and Fatemi demonstrated by Western blots an increased level of GFAP in superior frontal cortex (BA9; by 45%), parietal cortex (BA40; by 75%) and in the cerebellum (by 49%) in subjects with autism." (PMID 25231243, 2014).
autism (continued). "However, when control boys were compared with boys with autism, the results for FMRP and GABRβ3 remained nonsignificant and total mGluR5 and GFAP remained significantly elevated, while the dimerized mGluR5/β-actin ratio lost significance (data not shown)." (PMID 21548960, 2011).